MYO7A (myosin VIIA)
Diseases named in the same sentence as MYO7A in open-access papers (continued):
Sharing a sentence is not in itself a finding about the gene and the disease.
Usher syndrome (continued). "Furthermore, elucidation of the three distinct forms of Usher Syndrome Type 1 demonstrated that USH1B, USH1C, and USH1D are distinct genetic disorders caused by mutations in three different genes, MYO7A, CHD23, and USH1C, respectively." (PMID 33671976, 2021). "Multiple laboratories have effectively used this split vector approach in preclinical models: first for the delivery of the erythropoietin genomic locus, but later for retinal disease genes caused by variants in the MYO7A gene (Usher syndrome, type 1B) and the ABCA4 gene (Stargardt disease)." (PMID 34768969, 2021). "MYO7A mutations may cause various phenotypes ranging from non‐syndromic hearing loss (DFNA11/DFNB2) to Usher syndrome (USH1B)." (PMID 32027099, 2020). "Most of these MYO7A mutations (more than 95%) cause Usher syndrome type 1." (PMID 29416772, 2018). "The genetic diagnosis was made before onset of RP in 10 young patients with apparently isolated hearing impairment: nine with Usher syndrome due to mutations in MYO7A and USH2A, and one with a peroxisome biogenesis disorder (PBD) due to compound heterozygous PEX26 mutations." (PMID 28944237, 2017). "In Usher syndrome and X-linked choroideremia, which also involve defects in melanosome movement into the apical processes due to loss of function of myosin VIIa and Rep1, respectively, the photoreceptors also gradually degenerate." (PMID 25690007, 2015). "Different MYO7A mutations might lead to a wide variety of phenotypes with different inheritance patterns, ranging from Usher syndrome type 1B, autosomal recessive nonsyndromic hearing loss (ARNSHL) (DFNB2), to ADNSHL (DFNA11)." (PMID 23451214, 2013). "Human Usher syndrome is a dual sensory deficit disorder involving both the audiovestibular and visual systems and in many cases a mutation in MYO7A will result in an Usher phenotype: congenital sensorineural hearing loss and retinitis pigmentosa identified by progressive loss of vision." (PMID 23251483, 2012). "Usher syndrome is heterogenous, both in terms of clinical presentation and genetic origin, with a number of diverse genes known to carry pathogenic mutations (Type 1: MYO7A, USH1C, PCDH15, CDH23, USH1G, and CIB2; Type 2: USH2A, ADGRV1, and WHRN; Type 3: CLRN1)." (PMID 38474133, 2024). "MYO7A variants may cause either NSHI or Usher syndrome (USH)." (PMID 39767564, 2024). "The MYO7A locus was targeted to recapitulate disruptions in Usher Syndrome type 1B, a sensory disorder we aim to model in rhesus macaques in the future by introducing premature stop codons in this conserved motor protein gene." (PMID 41614797, 2025). "The development of therapeutic strategies for Usher syndrome has significantly advanced over the past decades with a focus on gene therapy, particularly for MYO7A-related Usher syndrome (USH1B)." (PMID 40149483, 2025). "MYO7A, involved in ADNSHL, ARNSHL, and Usher syndrome type 1B, was associated with H-both only for SKAT-O." (PMID 40055553, 2025). "Most previous papers reported only on Usher syndrome cases or a limited number of ADNSHL or ARNSHL patients, so the prevalence as well as the detailed clinical characteristics for ADNSHL and ARNSHL MYO7A-associated HL has been unclear." (PMID 38594301, 2024). "The most frequently implicated gene in cases of Usher syndrome was USH2A, containing disease-causing biallelic variants for 33.9% of families, followed by MYO7A in 24.2% of all families." (PMID 38189974, 2024). "The fly orthologue candidates of Usher syndrome genes MYO7A (crinkled in fly), WHRN (dyschonic in fly), USH1C (CG5921 in fly), and PCDH15 (Cad99C in fly) were localized or expressed in the actin-rich scolopale cells, consistent with our previous findings." (PMID 38412189, 2024). "Mutation in the MYO7A results in Usher syndrome type 1B (USH1B), the predominant form of Usher syndrome, a condition characterized by deafness and blindness." (PMID 39195247, 2024).
Usher syndrome (continued). "At least 9 causative genes have been found and identified to be responsible for Usher syndrome: Five for USH1 (MYO7A, USH1C, CDH23, PCDH15, and USH1G), three for USH2 (USH2A, ADGRV1, and WHRN) and one for USH3 (CLRN1)." (PMID 38984112, 2024). "In Usher syndrome, a multigenic disease characterized by sensorineural deafness and progressive retina degeneration, mutant Chd23, Harmonin, and Myo7a proteins impaired the formation and trafficking of the complex and triggered ER stress leading to cell death." (PMID 36959542, 2023). "The MYO7A (USH1B) gene represents an attractive target for CRISPRa therapy, as it exceeds the capacity of AAV vectors and is associated with Usher syndrome (USH), the most common form of genetic deafblindness." (PMID 37852949, 2023). "Five genes (USH2A, USH1G, USH1C, MYO7A, and PCDH15) were associated with Usher syndrome from Africa." (PMID 34609590, 2022). "To date, hundreds of MYO7A variations have been detected in people suffering from Usher syndrome, and about 30 of them have been clearly characterized in 25 DFNB2 families." (PMID 36164746, 2022). "Still, we found genes like Myo7a (Myosin VIIA), which is associated with Usher syndrome, to be dysregulated in Tgfbr2ΔOC retinae." (PMID 35269767, 2022). "Most of the syndromic diagnoses masquerading as NSHL were related to Usher syndrome (eight patients with causative mutations in the USH2A gene, three in the MYO7A gene, and one in the ADGRV1 gene)." (PMID 36555390, 2022). "Although the clinical data to date indicate the NSHL phenotype in this family, the diagnosis of Usher syndrome cannot be totally excluded since MYO7A‐related Usher syndrome usually presents with late‐onset retinal pigmented epithelium." (PMID 36164746, 2022). "The large cohort reported here illustrates once more the known genetic heterogeneity of Usher syndrome due to MYO7A and USH2A alterations." (PMID 34948090, 2021). "In conclusion, we report a natural knockout of the MYO7A gene, providing an interesting model to study Usher syndrome." (PMID 33955556, 2021). "In a familial case of Usher syndrome, a novel MYO7A (MIM *276903) intragenic deletion encompassing exons 20–23 was identified." (PMID 31736247, 2020). "For example, patients with a diagnosis of Usher syndrome type 1B (MIM *276900) show profound congenital hearing impairment, retinitis pigmentosa, vestibular dysfunction, and biallelic causal variants in MYO7A." (PMID 33187236, 2020). "In whirler mouse (Usher syndrome type 2D) photoreceptors, rhodopsin was found to be mislocalized, as were both rhodopsin and blue cone opsin in Myo7a mutant mice (Usher syndrome type 1B) and zebrafish." (PMID 31998945, 2020). "Currently, up to 13 genes have been associated with Usher syndrome: MYO7A, USH1C, CDH23, PCDH15, USH1G, and CIB2 are responsible for USH1, although the role of CIB2 in the Usher syndrome has recently been put on doubt." (PMID 31231422, 2019). "In a phase I/II trial sponsored by Sanofi, UshStat, an EIAV lentiviral vector carrying the wild-type MYO7A gene, is being administered subretinally to 18 patients with either Usher syndrome or retinitis pigmentosa (ClinicalTrials.gov #NCT01505062)." (PMID 30486314, 2018). "MYO7A mutations are responsible for nonsyndromic autosomal recessive hearing loss (DFNB2), autosomal dominant hearing loss (DFNA11), and Usher syndrome." (PMID 28472130, 2017). "Nonviral vectors developed through studies on vector capacity have increased the number of target genes, and genes such as CEP290 in LCA, ABCA4 in SMD, and MYO7A in Type 1 Usher syndrome are currently within capacity." (PMID 29326851, 2017). "Up to date, majority of mutations identified in MYO7A were associated with ARNSHL and Usher syndrome and few number of these mutations were associated with ADNSHL (DFNB11)." (PMID 28451532, 2017).
Usher syndrome (continued). "The family was found to segregate novel mutations of two different genes: myosin VIIA (MYO7A), which causes type 1 Usher syndrome, and phosphodiesterase 6B, cyclic guanosine monophosphate-specific, rod, beta (PDE6B), which causes nonsyndromic RP." (PMID 23882135, 2013). "Families 5, 6, and 7 appeared to have candidate mutations or variants in MYO7A, CDH23, PCDH15, and USH2A, all of which are associated with Usher syndrome." (PMID 24164807, 2013). "It is well understood that mutations in the MYO7A gene can underlie certain forms of syndromic and non-syndromic deafness in the human population, specifically non-syndromic dominant (DFNA11) and recessive (DFNB2) deafness and Usher Syndrome type 1B (USH1B)." (PMID 23251483, 2012). "It links proteins that are involved in the Usher syndrome, such as myosin VIIa, harmonin b, cadherin-23, protocadherin-15 and VLGR1b." (PMID 21479269, 2011). "Recessive mutations of the myosin VIIA (MYO7A) gene are reported to be responsible for both a deaf–blindness syndrome (Usher type 1B [USH1B] and atypical Usher syndrome) and nonsyndromic hearing loss (HL; Deafness, Neurosensory, Autosomal Recessive 2 [DFNB2])." (PMID 21031134, 2010). "Usher syndrome type 1B (USH1B) is a rare inherited disorder characterized by congenital deafness and progressive retinitis pigmentosa, caused by biallelic pathogenic variants in the MYO7A gene." (PMID 41528484, 2026). "IMPG2-mutant ROs showed photoreceptor outer segment abnormalities, while MYO7A-deficient ROs, associated with Usher syndrome type 1B, did not exhibit overt photoreceptor death." (PMID 39422807, 2025). "Although our findings provide useful insights into the performance of BE3 and BE3-Y130F at the MYO7A locus, a clinically relevant target for modeling Usher syndrome, it is difficult to draw broad conclusions about their overall efficiency and editing characteristics based on a single genomic site." (PMID 41614797, 2025). "In addition to MYO7A, four genes encoding the tip-link complex, USH1C, SANS, CDH23 and PCDH15, are associated with Usher syndrome type 1." (PMID 38562617, 2024). "USH2A and MYO7A were responsible for most type II and type I Usher syndrome cases, respectively." (PMID 38189974, 2024). "One functional study has demonstrated that mutations in MYO7A weakens its ability to form MYO7A/USH1C/USH1G complex which impairs phase separation, resulting in an abnormal tip-link densities and causing hearing and vision loss in Usher syndrome patients." (PMID 37985665, 2023). "NHP models of Usher syndrome are particularly urgently needed because rodent models of USH1 fail to show a retinal degeneration phenotype due to differences in the cellular distribution of MYO7A expression." (PMID 35710827, 2022). "The MYO7A gene is known to cause autosomal dominant or autosomal recessive non‐syndromic HL (DFNA11/DFNB2) as well as Usher syndrome (USH1B), which is characterized by congenital, bilateral, profound sensorineural HL, vestibular areflexia, and adolescent-onset retinitis pigmentosa (RP)." (PMID 34824372, 2022). "Potential causative variants were identified in genes associated with nonsyndromic hearing loss (CIB2, COL11A1, ILDR1, MYO15A, TMPRSS3, and WFS1), nonsyndromic hearing loss or Usher syndrome (CDH23, MYO7A, PCDH15, and USH2A), and other syndromic forms of hearing loss (CHD7, OPA1, and SPTLC1)." (PMID 34837038, 2022). "Finally, this 'natural knockout' will increase our understanding of the functioning of the MYO7A gene and provides a potential model for Usher syndrome in humans." (PMID 33955556, 2021). "Lentiviruses (LVs) are retroviruses with a larger packing capacity (8 kb), which makes them a compelling alternative to AAV vectors for those IRDs whose causative gene coding sequence exceeds the 4.7 kb limit, such as ABCA4-related Stargardt's disease and MYO7A-related Usher's syndrome type 1B." (PMID 34722588, 2021).
Usher syndrome (continued). "For example, some variants of MYO7A are associated with dominant (DFNA11) or recessive (DFNB2) inheritance of non-syndromic deafness, while the majority of MYO7A pathogenic variants cause Usher syndrome (USH1B)." (PMID 32987832, 2020). "Myosin VIIa mutations cause Usher syndrome USH1B and are also implicated in non-syndromic DFNA11 and DFNB2." (PMID 33228215, 2020). "The efficacy of both oversized and dual AAV vectors in the retina has been evaluated in a number of studies using different reporter and therapeutic genes, such as ABCA4 and MYO7A mutated in Stargardt disease (STGD1) and Usher syndrome type 1B (USH1B), respectively." (PMID 30970639, 2019). "Besides the USH2A gene, Usher syndrome also was caused by ABHD12 (1; 5%), CLRN1 (1; 5%), and MYO7A (8; 40%) genes." (PMID 30374144, 2018). "Mutations in PCDH15 and MYO7A may lead to both non-syndromic hearing loss (DFNB23 and DFNB2, respectively) and Usher syndrome type 1 (USH1F and USH1B, respectively)." (PMID 26011067, 2015). "Several members of the myosin gene family have been implicated in hearing loss, including MYO7A, where mutations in humans are responsible for causing non-syndromic dominant (DFNA11;) and recessive (DFNB2;) deafness and the deaf-blindness condition Usher Syndrome type 1B (USH1B;)." (PMID 23251483, 2012). "MYO7A is one of several genes responsible for the human Usher syndrome (USH)." (PMID 21479269, 2011). "In particular, three genes implicated in Type 1 Usher syndrome (CDH23, MYO7A and USH1C), while selected for the resequencing arrays, were not incorporated in the HHL APEX array; a separate APEX array for this group of disorders was already available when the HHL APEX array was originally designed." (PMID 20668687, 2010). "Myosin VIIA has been implicated in recessively inherited Usher syndrome type 1B (USH1B), atypical Usher syndrome (USH3), nonsyndromic recessive (Deafness, Neurosensory, Autosomal Recessive 2 [DFNB2]), and dominant (DFNA11) hearing loss (HL)." (PMID 21031134, 2010). "Myosin VIIA plays an important role in retinal photoreceptor cells, the pigment epithelium and inner ear; therefore, mutations in MYO7A result in a spectrum of phenotypes ranging from Usher syndrome type 1B to recessive non-syndromic hearing loss (DFNB2) and autosomal dominant hearing loss (DFNA11)." (PMID 40852359, 2025). "For example, variants of MYO7A are associated with both autosomal dominant (DFNA) and recessive (DFNB) nonsyndromic hearing loss as well as Usher syndrome type 1 (USH)." (PMID 38562617, 2024). "The prevalence of MYO7A-assocciated ADNSHL in autosomal dominant or maternal inheritance HL patients was 4.06% (91/2,243), while it was 0.38% (25/6,163) for ARNSHL patients and 0.32% (21/6,163) for MYO7A-associated Usher syndrome cases among autosomal recessive or sporadic HL patients." (PMID 38594301, 2024). "The potential, therefore, for treatment of Usher syndrome using certain AAV-based vectors is high, but the large size of some Usher genes, including some of the most common forms of Usher such as USH1B (MYO7A), does present unique challenges for the field." (PMID 32733204, 2020). "As a result, expanded capacity vectors can now accommodate genes such as CEP290, ABCA4, and MYO7A, genes responsible for LCA, SMD, and Type 1 Usher syndrome, respectively." (PMID 29326851, 2017). "Genetic counseling prior to analysis of genes potentially revealing Usher syndrome (CDH23, PCDH15 and MYO7A) is important and this should be explained to parents who agree to have this type of diagnostics performed for their child." (PMID 22607986, 2012). "Variants in the MYO7A gene might be responsible for autosomal dominant (OMIM #601317, DFNA11) and autosomal recessive deafness (OMIM #600060, DFNB2), as well as Usher syndrome (OMIM #276900, USH1), characterized by HL and retinopathy." (PMID 37108562, 2023). "The medical examination of MYO7A and PCDH15 patients showed that they had Usher syndrome type 1." (PMID 34609590, 2022).
deafness (72 papers, 2008 to 2026). An inherited or acquired condition characterized by the complete loss of the ability to hear from one or both ears. "Myosin-VIIA (MYO7A) is an unconventional myosin responsible for syndromic (Usher 1B) or nonsyndromic forms of deafness in humans when mutated." (PMID 39746042, 2025). "Mice homozygous for Myo7a mutations exhibit the characteristic shaker‐1 phenotype, which includes deafness, hyperactivity, head‐tossing and circling." (PMID 41015536, 2025). "MYO7A was the first deafness gene identified in humans causing both syndromic (USHER 1B) and non‐syndromic recessive deafness." (PMID 41015536, 2025). "Several recessive mutations have been identified in Myo7a, all of which cause defects in the cochlear hair cells and lead to deafness, though the onset and progression of the dysfunction vary." (PMID 41015536, 2025). "Mutations in Myo7a cause syndromic (Usher 1B) or nonsyndromic deafness in humans (16, –18) and deafness in mice." (PMID 39746042, 2025). "Mutations in MYO7A, the gene encoding the unconventional myosin 7a, cause hereditary deafness in mice and humans." (PMID 41015536, 2025). "Mutations in MYO7A affect the development of retinal photoreceptors and the mechanosensory stereocilia of hair cells, thereby causing a progressive deafness/blindness syndrome called Usher Syndrome 1B." (PMID 38100419, 2023). "In human and mouse, dominant loss‐of‐function variants in MYO7A have been described that cause deafness." (PMID 33955556, 2021). "Usher syndrome type B, or USH1B, is the most common disease resulting from MYO7A mutations, which is characterized by both loss of vision and profound deafness." (PMID 33718386, 2021). "The 11-aa peptide specific for MYO7A-C is present and sequence conserved in humans, but its short size makes a deafness mutation specifically affecting the long MYO7A isoform unlikely." (PMID 32350269, 2020). "All subjects with USH1 and biallelic MYO7A mutations were diagnosed with deafness and vestibular function impairment within their first 18 months of life." (PMID 29142287, 2017). "One example is Myo7a (myosin VIIA), in which deafness mutations affect the development and function of the mechanically sensitive stereocilia of hair cells." (PMID 27525485, 2016). "Here, we describe a novel ubiquitination pathway in Drosophila that functions to regulate the activity and physical interaction of two proteins implicated in deafness, Myosin II and Myosin VIIa." (PMID 27331610, 2016). "Despite intense investigation, the mechanisms by which loss of MYO7A results in deafness and blindness are poorly understood." (PMID 26960254, 2016). "A recent study revealed that many deafness-causing mutations occur in this domain, and provided mechanistic explanations for known deafness-causing mutations in MYO7A MyTH4-FERM using structure-based sequence analysis." (PMID 23865914, 2013). "We report two additional mouse models of deafness with novel mutations in the Myo7a gene, identified through an ENU mutagenesis screen." (PMID 23251483, 2012). "The Myo7a816SB mutation, which results in a 10‐amino‐acid deletion in the MYO7A motor head core, also causes severe hair bundle abnormalities from early stages of development and profound deafness." (PMID 41015536, 2025). "Notably, mutations in both OTOG and MYO7A have been associated with deafness in humans and in mice, but only MYO7A mutations have been associated with hydrocephalus." (PMID 38100419, 2023). "Missense mutation of R243 in unconventional myosin VIIa results in deafness." (PMID 35163146, 2022). "Therefore, mutations that affect myosin II alter how the protein interacts with myosin VIIa, which explains why myosin II is associated with deafness in humans." (PMID 27331610, 2016).